RHOB (ras homolog family member B)
Diseases named in the same sentence as RHOB in open-access papers (continued):
Sharing a sentence is not in itself a finding about the gene and the disease.
periventricular leukomalacia (1 paper, 2024). Periventricular leukomalacia (PVL) is a brain injury disorder characterized by the death of the white matter of the brain due to softening of the brain tissue. "In this study, rabbit models were generated to mimic the human RhoB p.S73F mutation using the SpG-BE4max system, and exhibited the typical symptoms of human CP, such as periventricular leukomalacia and spastic-dystonic diplegia." (PMID 39080495, 2024). "A rabbit model with the RhoB p.S73F mutation was established, which successfully replicated the progression of human CP, exhibiting typical symptoms, such as periventricular leukomalacia and spastic-dystonic paraplegia." (PMID 39080495, 2024).
psoriasis (1 paper, 2012). An autoimmune condition characterized by red, well-delineated plaques with silvery scales that are usually on the extensor surfaces and scalp. "In SSc, the newly reported candidate genes and risk loci include CD247, MHC, IRF5, and STAT4 gene regions, psoriasis susceptibility 1 candidate (PSORS1C) 1, TNIP1, and putative one close to ras homolog gene family, member B (RHOB) gene." (PMID 22110541, 2012).
retinal degeneration (1 paper, 2021). Degeneration of the retina. "The SLN formulation initially developed with RhoB, as the hydrophilic cargo, was validated with a real drug for retinal degeneration (i.e., CN03)." (PMID 35056970, 2021).
type 1 diabetes (1 paper, 2017). "Small-molecule inhibitors of RhoB have not been described, although molecules that target RhoA, Rac and Cdc42 have been, including Rac inhibitors studied in models of type 1 diabetes and collagen-induced arthritis." (PMID 28882929, 2017).
ZIKV infection (1 paper, 2021). "Further investigation identified the GTPase domain of RhoV to be critical for its proviral phenotype, while siRNA-mediated knockdown of RhoB, another Rho GTPase, and Pak1, the direct effector of RhoV, leads to reduced ZIKV infection." (PMID 34834920, 2021).
tumor (143 papers, 2002 to 2025). "MVP dysfunction in tumor cells causes PAg accumulation, resulting in the activation of RhoB and its repositioning from the nucleus to the vicinity of BTN3A1." (PMID 40558272, 2025). "Reviewing the results of previous studies on the role of RhoB in cancers, RhoB has been implicated in both oncogenic and tumor suppressor functions, highlighting its complex involvement in cancer development and progression." (PMID 38355625, 2024). "Our results support that tumor cells with a PTEN loss of function induce high levels of RHOB expression and enhanced migration dependent on a 3D environment; however, durotaxis is only active in the presence of PCL." (PMID 34680293, 2021). "Analyzing human tumor and normal tissues, they found that RhoB is highly expressed in the tumor-associated blood vessels compared with blood vessels of adjacent normal tissue, suggesting that RhoB is important for tumor vasculature." (PMID 32992837, 2020). "This study demonstrates for the first time that Vγ9Vδ2 T cell activation by PAg-treated tumor cells can be variable depending on several factors such as oncogenic mutation, RHOB activity, and surface markers." (PMID 32733462, 2020). "We report that RASSF1A, a key-regulator of cytoskeleton encoded by a tumor-suppressor gene on 3p chromosome, is involved in TNTs formation in bronchial and pleural cells since controlling proper activity of RhoB guanine nucleotide exchange factor, GEF-H1." (PMID 30305100, 2018). "Then, a reciprocal experiment where rhoB+/− and rhoB−/− tumors were grown in wild-type hosts demonstrated that rhoB loss in tumor cells was sufficient to reduce tumor growth even in a rhoB+/+ environment." (PMID 29385717, 2018). "Wild-type (rhoB+/+) tumors grown in rhoB+/− and rhoB−/− hosts demonstrated that the RhoB-deficient stroma was adequate to restrict tumor growth of rhoB+/+ cells." (PMID 29385717, 2018). "In support of its role as a negative modifier of cancer progression, targeted deletion of RHOB in mice can increase tumor formation initiated by Ras mutation." (PMID 28146424, 2017). "The underlying mechanism of RHOB‐mediated tumor suppression is only partially understood; however, we have shown that RHOB controls cell survival and invasion through PP2A‐mediated AKT dephosphorylation." (PMID 28003335, 2017). "RhoB functions as tumor suppressor in that loss of RhoB is frequently correlated with enhanced migration and invasion of cancer cells." (PMID 28323887, 2017). "Another up regulated gene in LFE animals and can be associated with inflammatory response is RHOB, a tumor suppressor that is associated to cell adhesion, motility, proliferation and survival." (PMID 26678995, 2015). "The use of primary lung fibroblasts isolated from RhoB deficient transgenic mice allowed us to identify activation of 3 major proteins in the secretome of TC-1 tumor cells cultured with conditioned media produced by these fibroblasts: MMP, bFGF and IL-6." (PMID 25635683, 2015). "The expression levels of miR-19a and RHOB exhibited in planted tumors illustrated that tumor progression did caused by increased miR-19a and down-regulated RHOB expression levels." (PMID 26041879, 2015). "Over-expression of RhoA, RhoB and Cdc42 in the tumours was found to be associated with the presence of lymph node metastases (P = 0.024, P = 0.004 and P = 0.047, respectively)." (PMID 23420497, 2013). "Despite sharing 86% homology to RhoA, in some cell types RhoB exerts more of a tumor-suppressor role, as loss of RhoB is associated with various types of human tumors and an increase in metastatic potential." (PMID 21373644, 2011). "The expulsion of RhoB is a hallmark of tumor cells targeted by Vγ9Vδ2 T cells." (PMID 40558272, 2025). "Due to the potential tumor-suppressing action of RhoB, the enhanced membrane association of RhoB may contribute to the inhibitory effects of atorvastatin/celecoxib combo on cancer cell proliferation." (PMID 36950511, 2023).
tumor (continued). "Moreover, as a tumor suppressor, downregulation of RhoB is associated with drug resistance in cancers." (PMID 35538494, 2022). "The driver mutation RhoB in C4 could promote tumor formation but also limit tumor invasion, which was consistent with that C4 has the lowest EMT signature score." (PMID 35223867, 2021). "Loss of RhoB expression also occurs very frequently in lung carcinogenesis as shown by many studies, and has been correlated with poorer outcomes, reinforcing its potential role as a tumor suppressor." (PMID 29385717, 2018). "Moreover, we tested RHOB expression on tumor biopsies of 11 patients at the moment of diagnostic and after relapse." (PMID 28003335, 2017). "In addition and interestingly RhoB deficiency in the stroma enhanced tumor cell migration but simultaneously stimulated pro-inflammatory signals (IL-6) that would impact on immune recruitment and favor anti-tumor immune response." (PMID 25635683, 2015). "In our present study, we investigated the crosstalk between stromal and carcinoma cells after irradiation and postulated that fibroblasts would promote TC-1 tumor migration after irradiation whereas deficiency in RhoB a protein described to be profibrogenic would prevent it." (PMID 25635683, 2015). "Loss of RhoB is often found in human cancers during tumor progression." (PMID 24223801, 2013). "Also, survival analyses did not reveal a prognostic significance of ERM/Rho protein expression, except for RhoB over-expression in the stromal compartment of tumours, which was found to be associated with a better patient survival." (PMID 23420497, 2013). "Moreover RhoB expression was associated with a low tumor grade and size, suggesting that RhoB expression is correlated with good prognosis markers." (PMID 23339407, 2013). "However, whether RhoB also regulates the inflammatory response in tumor cells and the underlying mechanisms of RhoB degradation needs to be further explored." (PMID 33553178, 2021). "Therefore, RhoB deficiency would indirectly enhance anti-tumor effect of radiation therapy." (PMID 25635683, 2015). "While classical RSGs are mostly oncogenic (except RhoB), the atypical RSGs, with some exceptions, are usually tumor-suppressive in nature." (PMID 41301045, 2025). "The group of Zsolt Sebestyen in 2016 found that RhoB modulates the capacity of tumor cells to stimulate Vγ9Vδ2 T cells by coordinating BTN3A1 within the cell membrane." (PMID 40558272, 2025). "Their role, however, is context-dependent—e.g., RhoB is tumor-suppressive in AR-null PCa but oncogenic in AR-positive tumors." (PMID 41301045, 2025). "Downregulation of RHOB expression has been observed to enhance migration following a decrease in intercellular adhesion, thereby promoting tumor progression." (PMID 39944833, 2025). "At the tumor’s leading edge, PTEN loss increases Ras homolog family member B (RHOB) expression, augmenting cell motility and adhesion." (PMID 39859381, 2025). "RhoB expression by immunohistochemistry in patients was increased from normal mucosa to tumor samples." (PMID 38355625, 2024). "For example, RHOB, which has been shown to control cell growth, differentiation, adhesion and migration in the tumour microenvironment, is highly expressed in the fibroblasts of L‐CRC." (PMID 39294858, 2024). "RhoB expression was increased from distant normal mucosa to primary tumor (McNemar p < 0.001) and from adjacent normal mucosa to tumor (McNemar p < 0.001)." (PMID 38355625, 2024). "We examined the intersection of the significantly upregulated proteins (top 10) in the two groups and identified five proteins, among which RhoB has been reported to be isoprenylated by GGPP or FPP and closely associated with tumor migration." (PMID 39521858, 2024). "The experimentalfindings indicated that AKT2/p-AKT/RhoB proteins played a crucial role inprolonging the survival cycle of tumor-bearing hosts." (PMID 38775545, 2024).
tumor (continued). "RhoB exhibits a dual role, functioning as both an oncogene and a tumor suppressor, depending on the stage of cancer development and progression." (PMID 39336777, 2024). "It is important to realize that the overall tumour expression of miR-21 and RHOB will be determined by a variety of cell types, such as immune cells and fibroblasts, as well as tumour cells." (PMID 36831632, 2023). "Since RhoB is largely understood to play a tumour-suppressor role in this disease, its down-regulation by elevated miR-21 levels would be detrimental, increasing the propensity for carcinogenic growth." (PMID 36831632, 2023). "This gene codes for RhoB, a Rho family GTPase that has been attributed a tumour suppressor role in many cancers." (PMID 36831632, 2023). "In the same bicalutamide-treated LNCaP tumours in which we observed miR-21 up-regulation, the RHOB mRNA levels were significantly reduced by Day 28, relative to those of the vehicle-treated tumours." (PMID 36831632, 2023). "In line with this, HCC tumour cell-derived exosomal miR-21-5p promotes TAM differentiation into an M2 phenotype by directly targeting Ras homolog family member B (RhoB)." (PMID 37894344, 2023). "For the prediction of survival time using RhoB expression on the tumor tissue of RT patients, accuracy rates obtained from the 10 individual CNNs are between 58% (InceptioResNetv2) and 67% (SqueezeNet) with GPU times of 9417 and 7915 seconds, respectively." (PMID 38014709, 2023). "We also observed that the 4 prognosis-associated genes RHOB, TALDO1, HLA-DPA1, and TKT were simultaneously elevated in the tumor and peripheral blood in patients with HCC." (PMID 35856557, 2022). "Tipifarnib is a farnesyltransferase inhibitor with the potential of increasing radiosensitivity by blocking activity of the RAS- and RhoB-oncogen pathways while also reducing tumor hypoxia by controlling MMP2 expression." (PMID 35503461, 2022). "Future study will be performed to elucidate the effect of TNFAIP1-mediated RhoB degradation on tumor inflammatory microenvironment and tumorigenesis." (PMID 33553178, 2021). "Several studies have shown that RHOA and RHOC positively contribute to tumor promotion, but the distinct role of RHOB as a tumor suppressor or an oncogene in cancer remains elusive." (PMID 34771549, 2021). "To unravel a more detailed analysis of the migration mode, we focused on U87 and MDA-MB-468 tumor cells with PTEN loss of function and high RHOB expression." (PMID 34680293, 2021). "On the other hand, more recent investigations have confirmed the downregulation of RHOB in some tumors, suggesting it has tumor suppressor activity." (PMID 34771549, 2021). "After injection of RhoB-labeled F3 or G7 peptides through tail veins for 1 h, the tumor-bearing mice were sacrificed and major organs along with tumors were collected to study the distribution of the peptides in vivo." (PMID 34150644, 2021). "Some studies have indicated that the oncogenic role of RHOB in tumor formation acts by inducing proliferation, angiogenesis, invasion, and migration." (PMID 34771549, 2021). "Our findings validate a significant role of specific PTEN genotypes along with RHOB signaling controlling cell morphology, durotaxis, adhesion, cellular plasticity and migration speed of tumor cells." (PMID 34680293, 2021). "In non-small cell lung cancer (NSCLC), DUXAP8 promotes tumor cell proliferation and invasion through epigenetically silencing Egr1 and RHOB." (PMID 34957112, 2021). "Our findings highlight a crucial role of TNFAIP1-induced RhoB degradation in regulating tumor inflammatory response." (PMID 33553178, 2021). "RhoB is a negative regulator of tumor, which can inhibit the biological functions of tumor invasion, migration and proliferation." (PMID 34093790, 2021). "In this study, we demonstrated that EVs from hypoxic GSCs containing miR-30b-3P significantly down-regulated the tumor-suppressor RHOB in the recipient tumor cells." (PMID 33408780, 2021).
tumor (continued). "Epithelial RHOB activation in response to several stress stimuli (DNA damage, hypoxia) counteracts tumor growth and cell migration/invasion, while promoting apoptosis, even in colon cancer cells." (PMID 33406731, 2021). "Although Rho GTPases, such as RhoA, RhoB, RhoC, and RhoE, promote tumor metastasis, the main roles of Rho GTPases remain unidentified." (PMID 33406809, 2021). "RhoB acts as a tumor suppressor by inhibiting tumor growth and inducing apoptosis in several types of cancer cells." (PMID 32089990, 2020). "Mokady and Meiri also showed that RhoA is overexpressed in many solid tumors, whereas RhoB acted more as a tumor suppressor with pro-apoptotic effects." (PMID 33162807, 2020). "Looking directly at whole-mount staining of mammary fat pads, they found an increased number of early tumor lesions in RhoB−/− (~10 lesions per fat pad) compared with RhoB+/− (~0.5 lesions per fat pad) mice." (PMID 32992837, 2020). "The isoforms RhoA, RhoB and RhoC constitute the Rho-like group whose RhoA and RhoC promoting tumor growth while RhoB is a tumor suppressor." (PMID 31983155, 2020). "Archived tumor samples from 106 women from three different cohorts showed that RhoA and RhoB were both more highly expressed in luminal tumors than in triple negative tumors." (PMID 33162807, 2020). "These location-dependent differences in RhoB function provide an explanation for the contradictory results on RhoB functioning as an oncogene or tumor suppressor." (PMID 31766364, 2019). "The unique nature of RhoB is particularly highlighted in its functional role as a putative tumor suppressor." (PMID 31200451, 2019). "Early evidence for altered membrane trafficking promoting the tumor phenotype has been provided for RhoB." (PMID 31766364, 2019). "Given RhoB’s role as a tumor suppressor, investigations have been conducted exploring RhoB for cancer prognosis and prevention." (PMID 31200451, 2019). "It will be interesting to determine the functions that are crucial for the tumour suppressive role of RhoB in NSCLC." (PMID 30549261, 2019). "RhoB usually acts as a tumor suppressor gene because it inhibits tumor cell proliferation and migration and promotes apoptosis of tumor cells by inhibiting PTEN/AKT pathway." (PMID 31011573, 2019). "RHOB has therefore been suggested to have a tumor suppressor role, while RHOA and RHOC are considered oncogenes." (PMID 31888022, 2019). "Therapies targeting Rho GTPases have great potential to inhibit angiogenesis-dependent tumor growth, especially when considering the high level of enrichment of some Rho GTPases including RhoB and RhoJ in diseased vessels." (PMID 31174284, 2019). "In the invasive part, some proteins (RHOB or fumarate hydratase) also exhibited an elevated AngioScore but these proteins have been indeed extensively studied in the context of tumor angiogenesis." (PMID 32642662, 2019). "In contrast, the role of RhoB is not clearly known, it acts as either an oncogene under some conditions or a tumor suppressor gene under others." (PMID 31331053, 2019). "The influence of RhoB activity on tumour development is less well studied and it appears that the small GTPase can play a two‐sided role." (PMID 30549261, 2019). "Subsequent knockdown and immunoprecipitation studies revealed that RASSF1A likely exerts its tumour suppressor effect by PP2A mediated dephosphorylation of GEF-H1 allowing subsequent stimulation of RhoB." (PMID 31623614, 2019). "The results showed that, compared with the DMSO treatment group, the mRNA and protein expression levels of PTEN and RhoB increased significantly in the tumor tissues of mice treated with atorvastatin, while the protein levels of p-AKT decreased significantly." (PMID 31011573, 2019). "Subsequently, the mRNA and protein expression level of RhoB, detected by RT-qPCR and Western blot, in the tumor tissues treated with ATO was higher than that treated with DMSO." (PMID 31011573, 2019).